SLC4A2 (solute carrier family 4 member 2)
Description:
Sodium-independent anion exchanger which mediates the electroneutral exchange of chloride for bicarbonate ions across the cell membrane. Plays an important role in osteoclast differentiation and function. Regulates bone resorption and calpain-dependent actin cytoskeleton organization in osteoclasts via anion exchange-dependent control of pH (By similarity). Essential for intracellular pH regulation in CD8(+) T-cells upon CD3 stimulation, modulating CD8(+) T-cell responses (By similarity).
Synonyms: BND3L; AE2; EPB3L1; HKB3; NBND3; OPTB9
Tractability: Small molecule: a structure with a bound ligand is known. Antibody: UniProt places it where antibodies can reach, with high confidence; its Gene Ontology location is reachable by antibodies, with high confidence; UniProt predicts a signal peptide or a membrane-spanning region. PROTAC: ubiquitination databases record sites on it; its protein half-life has been measured.
Gene: Protein-coding gene on chromosome 7 (151,057,210 to 151,076,527, forward strand). Ensembl gene ENSG00000164889.
Subcellular location: Apical cell membrane (Isoform A); Basolateral cell membrane; Apical cell membrane (Isoform B1); Apical cell membrane (Isoform B2)
Subcellular location (Human Protein Atlas): Nuclear speckles; Plasma membrane; Cytosol
Pathways (Reactome):
Transport of small molecules: Bicarbonate transporters
Gene Ontology:
Molecular function: protein binding; monoatomic anion transmembrane transporter activity; solute:inorganic anion antiporter activity; chloride:bicarbonate antiporter activity; enzyme binding
Biological process: osteoclast differentiation; amelogenesis; bicarbonate transport; monoatomic anion transport; negative regulation of CD8-positive, alpha-beta T cell differentiation; negative regulation of CD8-positive, alpha-beta T cell proliferation; positive regulation of enamel mineralization; regulation of actin cytoskeleton organization; regulation of bone resorption; regulation of intracellular pH; chloride transmembrane transport; digestive tract development; monoatomic anion transmembrane transport; spermatogenesis; transmembrane transport
Cellular component: apical plasma membrane; basolateral plasma membrane; focal adhesion; membrane; plasma membrane
Genetic constraint (gnomAD): Loss-of-function variants: 35 observed, 110.59 expected, observed/expected ratio (o/e) 0.32, 90% interval 0.24 to 0.42. The upper end of that interval is the gene's LOEUF score, 0.42, which puts it in group 1 of 6, group 1 being the genes least tolerant of losing a copy. Missense variants: 1,248 observed, 1,696.9 expected, observed/expected ratio (o/e) 0.74, 90% interval 0.7 to 0.77. Synonymous variants: 708 observed, 710.86 expected, observed/expected ratio (o/e) 1, 90% interval 0.94 to 1.06.
Homologues: Orthologues: chimpanzee SLC4A2 (99% identical), macaque SLC4A2 (99% identical), mouse Slc4a2 (94% identical), rat Slc4a2 (94% identical), guinea pig SLC4A2 (93% identical), rabbit SLC4A2 (91% identical), pig SLC4A2 (90% identical), dog SLC4A2 (88% identical), tropical clawed frog slc4a2 (69% identical), zebrafish slc4a2b (67% identical), zebrafish slc4a2a (63% identical), Drosophila melanogaster Ae2 (39% identical), and 3 more. Paralogues in human: SLC4A3 (58% identical), SLC4A1 (43% identical), SLC4A7 (33% identical), SLC4A10 (32% identical), SLC4A4 (32% identical), SLC4A8 (32% identical), SLC4A5 (30% identical), SLC4A9 (28% identical), SLC4A11 (17% identical).
Diseases named in the same sentence as SLC4A2 in open-access papers:
SLC4A2 is named in the same sentence as 32 diseases in open-access papers, as found by Europe PMC text mining. Sharing a sentence is not in itself a finding about the gene and the disease. The quoted sentences say what the papers report.
osteopetrosis (7 papers, 2010 to 2025). Osteopetrosis, also known as marble bone disease, is a descriptive term that refers to a group of rare, heritable disorders of the skeleton characterized by increased bone density on radiographs. "Bi-allelic SLC4A2 loss-of-function mutations in mice and cattle lead to osteopetrosis with osteoclast deficiency." (PMID 37761812, 2023). "SLC4A2 is required for proper osteoclast differentiation and function in mice, and mutations in bovine SLC4A2 are associated with osteopetrosis in Red Angus cattle." (PMID 33044947, 2020). "Mice deficient in all SLC4A2 isoforms, as a result of targeted replacement of exons 14-17 with A the neomycin resistance gene, fail to resorb bone and develop severe osteopetrosis." (PMID 20507629, 2010). "We have identified a deletion mutation in the bovine SLC4A2 gene that is associated with osteopetrosis in Red Angus cattle." (PMID 20507629, 2010). "In this study, we describe the clinical presentation and histopathology of osteopetrosis in Red Angus cattle, the mapping of the disease locus and the identification of a ~2.8-kb deletion mutation disrupting the SLC4A2 gene." (PMID 20507629, 2010). "In Red Angus cattle, a deletion mutation in SLC4A2 is associated with an osteopetrosis phenotype." (PMID 33451291, 2021). "Recently, a deletion mutation in the SLC4A2 gene, encoding the anion exchanger AE2, has been found to underlie osteopetrosis in Red Angus cattle." (PMID 24159188, 2014). "By analyzing SLC4A2 transcripts present in a known osteopetrosis carrier, we have confirmed the presence of a previously unannotated first exon identified in dbEST, and defined the biological relevance of the SLC4A2 deletion mutation." (PMID 20507629, 2010). "We further demonstrate complete concordance between the homozygous deletion genotype and the osteopetrosis phenotype, and confirm the presence of both normal and mutant SLC4A2 transcripts in a known carrier of the disease." (PMID 20507629, 2010). "It is interesting that no mutations in human SLC4A2 have been described to date in the context of osteopetrosis or any other hereditary disease." (PMID 20507629, 2010). "To test the hypothesis that the biological consequence of the deletion mutation is the formation of a transcript lacking exons 2 and 3, we performed 5' RACE to examine the cDNA ends of any SLC4A2 transcripts present in a known osteopetrosis carrier." (PMID 20507629, 2010). "Three reports published during the course of this study have indicated that, in mice, SLC4A2 is required for both the differentiation and bone-resorbing function of osteoclasts, and importantly, mice lacking this protein exhibit severe osteopetrosis." (PMID 20507629, 2010).
Hypertension (3 papers, 2009 to 2023). The presence of chronic increased pressure in the systemic arterial system. "In total, 12 markers in 7 genes (ADRA2A, LEP, LEPR, PTGER3, SLC2A1, SLC4A2, SLC8A1) revealed considerable association (P<10−3) either with SBP, DBP, and/or hypertension (HYP)." (PMID 19562039, 2009). "Dysfunctions of SLC4A2 encoding AE2 and SLC4A7 encoding NBCn1 are associated with hypertension." (PMID 37082243, 2023). "The inhibitory role of NBCn1 and AE2 in renal sodium reaborption indicates that the development of hypertension associated with the dysfunction of SLC4A7 and SLC4A2 could be the result of renal sodium retention." (PMID 37082243, 2023).
primary biliary cholangitis (3 papers, 2018 to 2024). Primary biliary cholangitis (PBC) is a chronic and slowly progressive cholestatic liver disease of autoimmune etiology characterized by injury of the intrahepatic bile ducts that may eventually lead to liver failure. "It has been reported that the activity of SLC4A2 is sensitive to pH, and its mutation is associated with primary biliary cirrhosis and autoimmune disease of the urogenital tract." (PMID 29851958, 2018). "The dysfunction of SLC4A2 participates in the pathogenesis of primary biliary cholangitis (PBC) that is a chronic, biliary obstructive, and autoimmune disease." (PMID 37894847, 2023).
biliary cirrhosis (2 papers, 2013 to 2024). "Key transcription factor Ppargc1a was significantly down-regulated in both tissues but particularly in adipose; which was accompanied by a 2-fold reduction in hepatic expression of the Cl(−)/HCO (−) anion exchanger 2 (Slc4a2), which is critically involved in the development of biliary cirrhosis." (PMID 23783067, 2013).
hepatocellular carcinoma (2 papers, 2014 to 2023). A malignant tumor that arises from hepatocytes. "Additionally, SLC4A2 was correlated with the proliferation and migration of the hepatoma cell." (PMID 37894847, 2023). "As SLC4A2 is correlated with the poor differentiation and prognosis of the ESCC, hepatocellular carcinoma, gastric cells, and colon cancer, it is considered an underlying target for diagnosing and treating these diseases." (PMID 37894847, 2023). "SLC4A2 (AE2) was found to be upregulated in CRC and hepatocellular carcinoma (HCC) and similar to SLC4A1 appears to interact with p16 in the cytosol." (PMID 24795638, 2014).
osteoporosis (2 papers, 2019 to 2021). A condition of reduced bone mass, with decreased cortical thickness and a decrease in the number and size of the trabeculae of cancellous bone (but normal chemical composition), resulting in increased fracture incidence. "A mutation (deletion) in gene SLC4A2 is related to osteoporosis in Red Angus cattle." (PMID 31600309, 2019). "XPR1, SLC4A2, and GNPTAB were previously reported to be related to osteoporosis, but GRAMD1B, ITGA6, and DUSP6 have never been studied with respect to any musculoskeletal-related diseases." (PMID 34475393, 2021).
breast carcinoma (1 paper, 2025). "These include SLC4A2, which encodes AE2, a bicarbonate-sodium exchanger which is upregulated in breast cancer contributing the metastasis." (PMID 41285961, 2025).
chondrodysplasia (1 paper, 2019). "Thus, it appears that mutations in solute carrier families (e.g., in genes SLC4A2 and SLC13A1), can cause bone disorders (e.g., chondrodysplasia) in livestock." (PMID 31600309, 2019).
clear cell renal carcinoma (1 paper, 2020). A malignant epithelial neoplasm of the kidney characterized by the presence of lipid-containing clear cells within a vascular network. "Interestingly, SLC4A2 have an unfavorable value for patients with clear cell renal carcinoma when analyzed separately." (PMID 32599841, 2020).
colorectal cancer (1 paper, 2024). A primary or metastatic malignant neoplasm that affects the colon or rectum. "SiRNA-mediated knock-down of the acid-loading AE SLC4A2 can raise steady-state pHi in colorectal cancer cells." (PMID 37999800, 2024). "Interestingly, it has recently been shown that lysosomal degradation of its closely related isoform, SLC4A2, is an adaptation mechanism to low pHe in colorectal cancer cells which provides a relatively alkaline cytoplasm." (PMID 37999800, 2024).
corneal dystrophies (1 paper, 2013). "Given the known involvement of SLC4A4 and SLC4A11 in corneal dystrophies, we speculate that the other two highly expressed genes in the uncultured corneal endothelium, SLC4A2 and SLC4A7, are worthy of being considered as potential candidate genes for corneal endothelial diseases." (PMID 23734078, 2013).
cyst (1 paper, 2021). A sac-like closed membranous structure that may be empty or contain fluid or amorphous material. "Both monolayer and cyst populations expressed the core functional transporter genes CFTR, SLC4A2, SCTR, and primary cilia related genes." (PMID 34764255, 2021).
deafness (1 paper, 2020). An inherited or acquired condition characterized by the complete loss of the ability to hear from one or both ears. "Based on the evidence presented here, we propose that the human SLC4A2 gene, the homologue of the zebrafish slc4a2b gene, is a potential deafness gene, and this should be confirmed in clinical studies." (PMID 33044947, 2020).
gastric cancer (1 paper, 2014). A primary or metastatic malignant neoplasm involving the stomach. "In gastric cancer, both upregulation and downregulation of SLC4A2 has been reported, and this was proposed to reflect that its expression is regulated by gastrin, the expression of which varies between different gastric cancers and cancer stages." (PMID 24795638, 2014). "Gastrin treatment decreased pHi of human gastric cancer cells in a manner correlating with the increased expression of SLC4A2." (PMID 24795638, 2014).
gastric disease (1 paper, 2021). "Importantly, KO mouse models for SLC26A7, SLC26A9, and SLC4A2 were described with gastric achlorhydria, which demonstrates that alterations found in our patients might explain gastric disease." (PMID 34944008, 2021).
mood disorder (1 paper, 2024). A cognitive disorder a disturbance in which the person's mood is hypothesized to be the main underlying feature. "SLC4A2 regulates brain pH balance and is linked to mood disorders, observed in individuals with suicidal tendencies." (PMID 39238930, 2024).
myelodysplastic syndrome (1 paper, 2014). A clonal hematopoietic disorder characterized by dysplasia and ineffective hematopoiesis in one or more of the hematopoietic cell lines. "It is to our knowledge unknown whether this intronic SNP alters the protein expression pattern of SLC4A2, and the causal link, if any, between SLC4A2 and myelodysplastic syndromes still needs to be established." (PMID 24795638, 2014).
osteosclerosis (1 paper, 2020). Abnormally high bone density. "Bovine osteosclerosis may be associated with a deletion of approximately 2.8 kb in exon 2 and part of exon 3 of the solute carrier family 4 member 2 (SLC4A2) gene encoding an anion exchanger." (PMID 32486017, 2020).
ovarian carcinoma (1 paper, 2017). A malignant neoplasm originating from the surface ovarian epithelium. "By analyzing ovarian cancer datasets with the cBioPortal, we found the highest frequency of AE2 (SLC4A2) gene amplification (TCGA Provisional, 10.0%; TCGA 2011, 4.4%), as compared to AE1 (SLC4A1) (TCGA Provisional, 0.3%; TCGA 2011, 0.3%) and AE3 (SLC4A3) (TCGA Provisional, 2.6%; TCGA 2011, 0.6%)." (PMID 28743911, 2017).
cancer (4 papers, 2014 to 2023). A tumor composed of atypical neoplastic, often pleomorphic cells that invade other tissues. "In ESCC, the decreased SLC4A2 expression facilitates intracellular alkalinization, which promotes cancer cell metabolism and is correlated with a poor prognosis." (PMID 37894847, 2023). "The expression of SLC4A2 can be inhibited by gastrin, leading to the inhibition of cancer proliferation." (PMID 37894847, 2023). "The expression of SLC4A2 was found to be regulated in quite a few cancers." (PMID 37894847, 2023). "As the inhibition of SLC4A2 expression can decrease the proliferation of cancer cells, it may have a function in promoting colorectal cell growth." (PMID 37894847, 2023). "Among the acid-loading transporter genes, the expressions of SLC4A1AP, SLC4A2, and SLC4A3 are up-regulated or remain unaltered in cancer tissues vs. controls across most of the 14 cancer types." (PMID 31071451, 2019). "The membrane transporter ABCC1 (MRP1), which confers multidrug resistance to cancer cells, was also enriched in the Panc-1 library, along with three other SLC transporters, SLC4A2, SLC30A1, and SLC12A7 (KCC4), plus the epidermal growth factor receptor EGFR and lipid transport protein ESYT2." (PMID 37295717, 2023). "Moreover, whereas in contrast to SLC4A1, SLC4A2 does to some extent localize to the plasma membrane in the cancer cells, it is not clear from the published studies whether the role of the exchanger in cancer progression involves both pHi regulation and p16 sequestration." (PMID 24795638, 2014).
immune disorders (1 paper, 2023). "SLC4A2 deficiency can change the pH balance of immune cells, resulting in immune disorders in PBC patients." (PMID 37894847, 2023). "The deficiency of SLC4A2 in PBC patients would make biliary cells more immunogenic and vulnerable to autoimmune injury, leading to immune disorders." (PMID 37894847, 2023).
infection (1 paper, 2024). The state of being infected such as from the introduction of a foreign agent such as serum, vaccine, antigenic substance or organism. "Later at 12dpi, all genes except for Slc4a2 were significantly upregulated in SEOV-infected rat LMECs, again suggesting that this pathway is more involved later during infection." (PMID 38536871, 2024).
SLC4A2 also shares sentences with these, for which no sentence is quoted: tumour (3 papers); autoimmune disease of the (1); bone disorder (1); Gastric Neuroendocrine Tumors (1); hereditary disease (1); liver cancer (1); mastitis (1); ovarian serous carcinoma (1); pycnodysostosis (1); sclerosteosis (1).